Y_RNA (Y RNA )
Gene: Miscellaneous RNA gene on chromosome 4 (82,944,738 to 82,944,845, reverse strand). Ensembl gene ENSG00000199530.
Homologues: Orthologues: chimpanzee Y_RNA (99% identical). Paralogues in human: Y_RNA (80% identical), Y_RNA (79% identical), RNY1P5 (78% identical), RNY1P6 (77% identical), Y_RNA (77% identical), Y_RNA (76% identical), Y_RNA (75% identical), RNY1P1 (74% identical), Y_RNA (74% identical), RNY1 (73% identical), Y_RNA (73% identical), RNY1P14 (72% identical), and 90 more.